FGFR1 (fibroblast growth factor receptor 1)
Diseases named in the same sentence as FGFR1 in open-access papers (continued):
Sharing a sentence is not in itself a finding about the gene and the disease.
osteoglophonic dysplasia (20 papers, 2013 to 2025). "Support derives from the fact that FGF23 overproduction is a characteristic feature of osteoglophonic dysplasia, a rare form of dwarfism due to gain-of-function FGFR1 mutations." (PMID 36943390, 2023). "Osteoglophonic dysplasia is due to activating mutations in FGFR1 (Fibroblast growth factor receptor 1)." (PMID 34910242, 2022). "We report a case and its 4-year follow-up of Osteoglophonic dysplasia (OD), a rare disease that disturbs both skeletal and dental development, which is usually caused by heterozygous FGFR1 mutations." (PMID 35148738, 2022). "Activating variants in FGFR1 were reported in patients with osteoglophonic dysplasia and hypophosphatemia, moreover in one family all family members with FGFR1 p.Y372C died due to affected respiratory function." (PMID 35432193, 2022). "Among 197 mutations in FGFR1, only three are reported in patients with osteoglophonic dysplasia (HGMD, accessed Nov 13, 2017)." (PMID 29280738, 2017). "In this regard, FGF23 is increased in osteoglophonic dysplasia, which is caused by activating mutations in FGFR1." (PMID 25089825, 2014). "Similarly, Y372C missense gain-of-function mutation in FGFR1 in osteoglophonic dysplasia (OGD) and systemic administration of activating antibodies to FGFR1 in mice elevate circulating FGF23 levels, but have the confounding effects of activation of FGFRs in both bone and kidney." (PMID 25089825, 2014). "An increase in serum FGF23 has been reported for one case of a rare genetic hypophophatemic disorder called osteoglophonic dysplasia (OGD) caused by a dominant activating FGFR1 mutation." (PMID 23451204, 2013). "The functional consequences of excess FGFR1 are manifest in osteoglophonic dysplasia (OGD), caused by gain-of-function (GoF) variants in the fibroblast growth factor receptor 1 (FGFR1), causing constitutive receptor activation." (PMID 41473314, 2025). "Osteoglophonic dysplasia, an extremely rare autosomal dominant disorder linked to FGFR1 (fibroblast growth factor receptor 1) mutations." (PMID 38929327, 2024). "Osteoglophonic dysplasia (OD) (OMIM number: # 166250), caused by FGFR1 mutation, is a rare disease that is characterized by stunting of stature, craniosynostosis, facial dysmorphism, brachydactyly stubby fingers and toes." (PMID 35148738, 2022). "In addition, activating mutations in human FGFR1 cause osteoglophonic dysplasia (OMIM #166250) associated with increased levels of FGF23 and hypophosphatemia, which also suggests that activated FGF/FGFR signaling may play a role in regulation of Fgf23 expression." (PMID 24710520, 2014). "Antibody-mediated activation of FGFR1 is potentially mimicking some aspect of osteoglophonic dysplasia (OGD), a rare genetic disorder characterized by a distinctive skeletal dysplasia caused by an activating FGFR1 germ line mutation." (PMID 23451204, 2013). "Further analyses were performed based on the rationale that activating mutations in FGFR1 produce the condition osteoglophonic dysplasia, which is characterized by low bone mineral density, nonossifying bone lesions, and fracture-healing deficits, findings seen in OI." (PMID 37796615, 2023). "Cranial malformations arise in a range of diseases that involve activation of FGF23 receptors, including osteoglophonic dysplasia (OGD) (FGFR1,), Crouzon and Apert syndromes (FGFR2,) and achondroplasia (FGFR3,)." (PMID 30808384, 2019).
small cell lung carcinoma (20 papers, 2013 to 2023). Small cell lung cancer (SCLC) is a highly aggressive malignant neoplasm, accounting for 10-15% of lung cancer cases, characterized byrapid growth, and early metastasis. "We used U2OS-R1 as a model cells stably producing FGFR1 and small cell lung cancer cells DMS114 characterized by high level of FGFR1 expression." (PMID 34635096, 2021). "A recent study has also suggested that elevated expression of both SOX2 and FGFR1 is correlated to poor prognosis in small cell lung cancer." (PMID 25010701, 2014). "Moreover, preclinical studies have shown that a subset of FGFR1-amplified small cell lung cancer is extremely sensitive to FGFR inhibition by PD173074, a specific FGFR1 inhibitor." (PMID 28030802, 2017). "Likewise, FGFR1 mRNA is exclusively spliced to generate FGFR1 IIIc in small cell lung carcinoma (NSCLC) cells lines." (PMID 23900974, 2013). "FGFR1 amplification is in 10−20% of patients with NSCLC150, 151, 152 and 5−7% of patients with small cell lung cancer." (PMID 37750089, 2023). "A similar effect was observed in other FGFR1-positive cells, DMS114, the small cell lung cancer cell line." (PMID 36276073, 2022). "FGFR1 gene amplification and protein expression were analyzed by fluorescence in situ hybridization and immunohistochemistry (IHC) in 208 SQCLC and 45 small cell lung cancers (SCLC)." (PMID 32207251, 2020). "A recent study on small cell lung cancer patients identified FGF10 amplification in 37.5% of patients and FGFR1 amplification in 25% of patients." (PMID 31958320, 2020).
brain tumors (18 papers, 2015 to 2025). "Primary brain tumors frequently exhibit deregulation of FGFR1 via mechanisms like gain-of-function mutations, kinase domain amplification, and translocation, predominantly with the partner gene TACC1." (PMID 41567627, 2025). "Overall, our findings provide mechanistic evidence on the driver effects exerted by multiple mutations in FGFR1 gene and shed new light on tumorigenic mechanisms during early-onset brain tumor formation." (PMID 41174249, 2025). "Our analyses demonstrate that FGFR1-IIIc isoform is the predominant variant across all pediatric brain tumor types analyzed." (PMID 34046693, 2021). "One of the recurrently mutated genes was FGFR1, encoding the fibroblast growth factor receptor 1, which was recently revealed as an oncogene in pediatric brain tumors." (PMID 29159601, 2018). "These mutations, specifically FGFR1 K656E and FGFR1 N546K, were also found in a whole exome sequencing of five ECCL-associated brain tumors." (PMID 41283481, 2025). "Among these cases (N546K or K656E mutated), we reviewed tumors with multiple hits in FGFR1 and found that they were exclusive to brain tumor types, with the hotspot K656E being the one more frequently accompanied by additional FGFR1 hits." (PMID 41174249, 2025). "Oncogenic fibroblast growth factor receptor 1 (FGFR1) tyrosinase kinase domain has been reported in brain tumors of various histologies." (PMID 35018490, 2022). "In this study, we discovered that the same FGFR1 hotspot residues as in certain brain tumors, Asn546 and Lys656 (also reported in 1 of 394 PCCs in the COSMIC database), are recurrently mutated in PCCs." (PMID 29159601, 2018). "The mechanisms of FGFR activation in brain tumors vary by tumor type, but include oncogenic FGFR3 and FGFR1 fusions, FGFR1 rearrangements, and FGFR1 mutations." (PMID 28468611, 2017). "Some recurrent aberrations affecting FGFR1 have been reported in pediatric brain tumors including hotspot point mutations and a novel internal duplication of the kinase domain termed TKD-duplicated or FGFR1 internal tandem duplication (FGFR1-ITD)." (PMID 27791984, 2017). "DDPCRTM is an easy and alternative method than whole-genome sequencing to detect FGFR1-ITD in FFPE brain tumors, in routine practice." (PMID 27791984, 2017). "By examining tumor grade of hotspot-positive brain tumor types, we found that multiple FGFR1 alterations are found in similar rates in both low-grade (grades 1–2) and high-grade (grades 3–4) cases, with a higher number of double-mutant cases identified in low-grade types." (PMID 41174249, 2025). "Performing FGFR1 sequencing analysis in driver-unknown low-grade brain tumors could yield up to 12% FGFR1 N546/K656 mutant cases." (PMID 35018490, 2022). "To study the impact of the mutations investigated so far on a model that could better recapitulate the molecular background of FGFR1-mutated brain tumors we used the human oligodendroglioma cell line (HOG) and we applied CRISPR/Cas9 to generate isogenic FGFR1-mutant HOG cell lines." (PMID 41174249, 2025). "The rates of alterations of the FGFR1, FGFR2, FGFR3, and FGFR4 genes in brain tumor patient samples were 1%, 1.5%, 1.7%, and 0.9%, respectively, and pediatric brain tumors had among the highest levels of FGFR gene family alterations among all brain tumor databases." (PMID 40510032, 2025). "In brain tumors, FGFR1 alterations are not restricted to tumor grade or a specific age group." (PMID 35018490, 2022). "Performing FGFR1 sequencing analysis routinely in non-diffusely growing driver-unknown low-grade brain tumors could yield up to 15% FGFR1 N546/K656 mutant cases." (PMID 35018490, 2022). "While FGFR1 was overexpressed in a variety of nonhematopoietic tumor types, PDGFRA was exclusively overexpressed in brain tumors, and FLT3 was exclusively overexpressed in acute leukemias." (PMID 31651965, 2019).
depression (18 papers, 2011 to 2025). "It was associated with increased phosphorylation of FGFR1 and thus its activation, which can help counteract depression induced atrophy of the hippocampus." (PMID 28270751, 2017). "The chronic unpredictable stress model causes anhedonia and is a model of depression that results in decreased (mRNA) Fgfr1 levels in the prefrontal cortex." (PMID 28439461, 2017). "This suggests that the loss of FGFR1 in dentate gyrus neurons is associated with an accelerated onset of depressive-like behaviors, implying a potential role of FGFR1 as a protective factor against the onset of depression." (PMID 40813470, 2025). "Furthermore, FGF2 and FGFR1 signaling in the prefrontal cortex is implicated in human depression and in rodent models of depression." (PMID 28674667, 2017). "Similar to the corticosterone-induced depression model, both Fgfr1 mRNA and FGFR1 protein levels were significantly increased in the CUMS group mice 4 weeks after stress exposure." (PMID 40813470, 2025). "Mice were then subjected to 1 week of corticosterone administration to induce depression, followed by optogenetic activation of FGFR1 in the dentate gyrus and EdU labeling." (PMID 40813470, 2025). "Future work will require the use of interface interfering peptides to finally determine the role of FGFR1-5-HT1A heterocomplexes in the FSL genetic model of depression." (PMID 29066953, 2017). "Changes in Fgfr1 expression, and FGF2 levels in the hippocampus are linked to major depression and anxiety, as well as to responses to antidepressants." (PMID 28439461, 2017). "The tgFgfr1-EGFP+ model can also be used to study additional stages in development, or Fgfr1 expression after environmental manipulations previously shown to alter Fgfr1 expression, including animal models for induced depression such as social defeat stress." (PMID 28439461, 2017). "In addition, increased expression of FGF-2 receptor (FGFR1) was found in the hippocampus of postmortem brains of patients with schizophrenia and major depression." (PMID 38414501, 2024). "Similarly, increased FGFR1 expression in the prefrontal cortex of patients with major depressive disorder has also been demonstrated." (PMID 38638441, 2024). "To investigate whether the effect of rhFGF21 on depression is mediated through the FGFR1 signaling pathway, we detected the expression levels of FGFR1 and p-FGFR1 by western blotting." (PMID 32184729, 2020). "We studied in the current work the disturbances in the FGFR1-5-HT1A heterocomplexes in a genetic rat model of depression, the Flinders sensitive line (FSL) rats of Sprague-Dawley (SD) origin, by means of neurochemical, neurophysiological and behavioral techniques." (PMID 29066953, 2017). "The raphe 5-HT1A autoreceptor when being part of the FGFR1-5-HT1A heteroreceptor complexes may have a beneficial role in depression by assisting in the recovery of 5-HT nerve cell trophism including 5-HT synthesis and storage." (PMID 29066953, 2017). "It is hypothesized that Fgf2 and Fgfr1 are downregulated in depression and anxiety, and this downregulation can be partially reversed by antidepressant treatment (Turner, Watson & Akil, 2012b; Turner, Watson & Akil, 2012a)." (PMID 28439461, 2017). "Furthermore, FGFR1 can interact with other type of receptors to play a role in depression." (PMID 30804785, 2019). "In depression, neuromodulation of neuronal networks in the raphe-hippocampal system and the cortical regions via 5-HT and fibroblast growth factor 2 involves either FGFR1-5-HT1A heteroreceptor complexes or the 5-HT isoreceptor complexes such as 5-HT1A-5-HT7 and 5-HT1A-5-HT2A." (PMID 28270751, 2017). "Using optogenetics (a method to control the signaling pathway of cells with light), they discovered a new pathway involving FGFR1, Notch and brain-derived neurotrophic factor (BDNF) proteins that promotes neurogenesis and reduces depression symptoms." (PMID 40813470, 2025).
depression (continued). "Here, we mainly concentrated on the reported depression-related FGF system members, including FGFR1, FGF2, FGF9, FGF21, and FGF22." (PMID 30804785, 2019). "It therefore became of interest to study the FGF2 and 5-HT1A agonist regulation of the FGFR1-5-HT1A heterocomplexes in the hippocampus and dorsal raphe in a genetic rat model of depression (FSL) vs. the control SD strain using the in situ PLA." (PMID 29066953, 2017). "A recent alternative hypothesis suggests that depression results from alterations in receptor activity due to formation of homoreceptor and heteroreceptor complexes involving receptor types including 5HT1A, 5HT7, galR1, and fibroblast growth factor receptor 1 (FGFR1)." (PMID 29375372, 2017). "Based on these and previous findings the hypothesis was tested if disturbances in the combined receptor agonist regulation of FGFR1-5-HT1A heteroreceptor complexes can take place at the behavioral and neurochemical levels in an animal model of depression." (PMID 29066953, 2017). "The hypothesis goes beyond the serotonin hypothesis of depression and moves into molecular integration performed in diverse 5-HT1A and other 5-HTR heterocomplexes where, e.g., fibroblast growth factor receptor 1 (FGFR1) and oxytocin receptor protomers participate." (PMID 33672070, 2021). "Alterations of astrocyte-enriched fibroblast growth factor (FGF) receptors observed here (upregulation of Fgfr3, downregulation of Fgfr1) may also be relevant to depression biology given the findings of altered expression of FGF receptors and ligands in depression." (PMID 23966905, 2013). "Although we did not identify any significant changes in Fgfr1 mRNA levels in leukocytes, an important reduction of ErbB3 mRNA levels emerged in depressed patients, suggesting that ErbB3 could be considered as a biomarker of depression." (PMID 22989054, 2012).
endometrial cancer (18 papers, 2014 to 2025). Primary or metastatic malignant neoplasm involving the endometrium (mucous membrane that lines the endometrial cavity). "Studies have shown that the methylation level of the FGFR1 promoter is low in various solid tumours, particularly in breast, head and neck, oesophageal, bladder and endometrial cancers." (PMID 40135140, 2024). "Other promising multikinase inhibitors are dovitinib, lucitanib, and ponatinib which are under investigation for endometrial cancer, FGFR1-amplified tumors and advanced squamous cell lung cancers, respectively." (PMID 27051190, 2016). "Additionally, widespread FGFR1 mRNA expression was observed in other solid tumour types, such as breast, head and neck, oesophageal, bladder and endometrial cancers." (PMID 40135140, 2024). "Somatic mutations in FGFR1, FGFR2, FGFR3, and FGFR4 genes are reported in endometrial cancer." (PMID 33193890, 2020). "To date, among the listed FGF traps, a promising molecule is FP-1039, a soluble FGFR1-Fc fusion protein that binds almost all FGFs, and thus inhibits growth of different tumor cell lines, including lung and endometrial cancer, as well as mesothelioma cell lines." (PMID 30134556, 2018). "FGFR1 and FGFR3 amplifications are also found in endometrial cancer through integrating genomic characterization of somatic copy number alterations." (PMID 33193890, 2020).
acute leukemia (17 papers, 2007 to 2025). A clonal (malignant) hematopoietic disorder with an acute onset, affecting the bone marrow and the peripheral blood. "Myeloid and lymphoid malignancies associated with chimeric FGFR1 kinases are the hallmark of stem cell leukemia and lymphoma syndrome (SCLL)." (PMID 35906694, 2022). "The subgroup of entities, composed by FGFR1 rearrangements, has a characteristic poor short-term prognosis and a high probability to transform to acute leukemias." (PMID 36698221, 2023). "Ponatinib was also tested in a patient with a FGFR1-rearranged neoplasm manifesting as a Bcr-FGFR1-positive trilineage T/B/myeloid mixed-phenotype acute leukemia." (PMID 30423915, 2018). "The only consistent association of FGFR1 abnormalities with cancer, however, involves the constitutive activation of a ligand-independent, chimeric FGFR1 kinase in Stem Cell Leukemia and Lymphoma syndrome (SCLL)." (PMID 27391347, 2016). "Although over expression of chimeric FGFR1 kinase consistently leads to the development of AML in the rare Stem Cell Leukemia and Lymphoma syndrome, we now show that overexpression of FGFR1 is also seen in up to 20% of non-syndromic, de novo AML." (PMID 27391347, 2016). "M/LN-eo with FGFR1 being rearranged presents most frequently as MPN with or without concomitant involvement by lymphoblastic lymphoma or acute leukemia and less like a myeloid, lymphoid, or mixed-lineage disease in the blastic phase, which can also be only extramedullary." (PMID 38254826, 2024). "When acute leukemia is treated and remitted, MPN appears with leukocytosis, splenomegaly, and isolated persistence of the FGFR1 rearrangement." (PMID 38254826, 2024).